CD44 (CD44 molecule (IN blood group))
Diseases named in the same sentence as CD44 in open-access papers (continued):
Sharing a sentence is not in itself a finding about the gene and the disease.
tumor (continued). "CKS1B knockdown significantly reduced the self-renewal capacity and number of CSCs, as evidenced by in vitro tumor sphere formation, increased CD44+CD24+/CD133+ cell populations, and decreased expression of CSCs markers (ABCG2, C-MYC, ALDH1, BMI-1)." (PMID 39897042, 2025). "CD44 is overexpressed during the initial stages of tumor development, migration, proliferation, and metastasis." (PMID 41440277, 2025). "Concurrently, the retention capacity of NK cells requires reinforcement through gene-editing approaches, including the overexpression of CD44 to bind hyaluronic acid on tumor surfaces, thereby extending cell residence time within tumor tissues." (PMID 41488873, 2025). "Conversely, low molecular weight HA exerts a pro-tumourigenic effect, competing with native-HA for binding to the CD44 receptor, thereby preventing the beneficial clustering of CD44 and enabling tumour progression by inhibiting Hippo signalling." (PMID 39852021, 2025). "METTL13-mediated CD44 mRNA decay in CRPC to promote tumor growth and metastasis, thereby promoting docetaxel treatment resistance." (PMID 41194259, 2025). "Bulk tumour cells and both AR and CD24low/CD44+ BCSCs effectively sensed cisplatin-ICLs, mounting a comparably robust FA/DSB response following pulse cisplatin treatment (2 h), as evidenced by FANCD2 and initial 53BP1 recruitment respectively." (PMID 39695328, 2025). "oHA’s unique molecular structure enables it to target tumor cells and inflammatory sites via receptor-mediated endocytosis (e.g., CD44 and RHAMM receptors), which improves drug delivery precision and therapeutic efficacy." (PMID 40284532, 2025). "PLGA nanoparticles help bypass these mechanisms by enhancing intracellular drug accumulation, enabling ligand-mediated active targeting (e.g., EpCAM, CD44), and triggered drug release within the tumor microenvironment." (PMID 41233827, 2025). "Expressions of CD44 and xCT in the tumor periphery were significantly higher in Group E than in Group NE." (PMID 40002787, 2025). "A tumor spheroid model revealed that the core bioink promotedBrCa cell proliferation, while the peripheral bioink enhanced migrationand invasiveness via CD44 and EMT marker upregulation." (PMID 41171302, 2025). "Further highlighting the pleiotropic role of CD44 in regulating different receptors, including Met, to promote cell plasticity and tumor growth, targeting CD44 with sTN58 led to a downregulation of the Met receptor." (PMID 40342488, 2025). "Meanwhile, the collagen–CD44 axis mediates directional migration of immune cells—diverting cytotoxic lymphocytes away from tumor parenchyma and toward the stroma, thereby facilitating immune escape." (PMID 41031085, 2025). "SC-RareFind is specifically designed to identify rare cells that constitute less than 5% of pancreatic cancer populations—such as CD44+CD24+ tumor stem cells—and employs optimized clustering algorithms to minimize stromal cell interference." (PMID 41463034, 2025). "Among these, CD44 serves as an adhesion molecule that promotes tumor cell invasion as well as migration." (PMID 40647654, 2025). "At the same time, we detected HCC related tumor stemness markers (CD44 and CD133) in these spheres and found that circRNA‐mTOR significantly promoted the expression of stemness markers." (PMID 40231634, 2025). "H4C4 is an anti-human CD44 IgG1 mAb that reduces tumor growth, metastasis, and post-radiation recurrence in pancreatic cancer." (PMID 41011286, 2025). "Interactions of SPP1+ TAMs were also examined in another study of CRC, where the SPP1+ TAMs were found to exhibit interactions with tumour cells via the binding of SPP1 and CD44 on tumour cells." (PMID 40954554, 2025). "To explore the potential significance of this phenomenon we performed deep sequencing of HT-29 xenograft tumor samples to identify differentially expressed canonical miRNAs and their 5’-isoforms following CD44 kd." (PMID 40438109, 2025).
tumor (continued). "Here, we present a novel method for the selective enrichment of CD44-expressing tumor cells from blood using thermoresponsive microgel surfaces functionalized with hyaluronic acid (HA)." (PMID 40988643, 2025). "MMP-9 and CD44, both involved in tumor invasion and metastasis, have demonstrated varying degrees of utility." (PMID 40422614, 2025). "Pseudotime trajectory, stemness evaluation, and cell-cell communication analyses explored how CD44+ tumor cells at the leading edge remodel the tumor microenvironment (TME)." (PMID 40069574, 2025). "The activated CD44 is predominantly expressed in cancerous tissues, leading to tumour cell survival, increased proliferation, enhanced motility, and cytoskeletal changes." (PMID 41155181, 2025). "Lastly, after confirming HA reduction in all three cell lines, we assessed its impact on tumor volume, CD44 (HA’s main receptor and potential BRCA regulator), HYAL1 (which responds to HA changes), and BRCA1/2 expression." (PMID 41373491, 2025). "The anti-CD44 monoclonal antibody A6 has been shown to inhibit tumor cell migration, invasion, and metastasis by blocking CD44-mediated signaling pathways." (PMID 40083943, 2025). "In the tumor biopsies, cells expressing CD44 and cells expressing CD133 were more prevalent in grade 1 tumors." (PMID 39888143, 2025). "CD44 cooperates with STAT3 in various tumor types, contributing to cancer invasion, metastasis, disease recurrence, and chemoresistance." (PMID 40438109, 2025). "For example, preclinical studies in GBM models have shown that CAR-T cells targeting either CD44 or CD133 alone yield only transient tumor control, followed by tumor recurrence." (PMID 40759634, 2025). "We then sorted CD44+ PD-1+ TIM-3- P14s from the TdLNs of tumor bearing mice and transferred them into separate B16F10GP tumor-bearing mice." (PMID 40229241, 2025). "Inflammatory CAFs (iCAFs)-like, myofibroblastic CAFs (myCAFs)-like cells and pro-tumorigenic neutrophils primarily located at the tumor edge, in proximity to CD44+ tumor cells." (PMID 40069574, 2025). "Specific markers such as OCT4, SOX2, NANOG, ALDH1, and CD44 are commonly used to identify CSCs, with CD44 glycoprotein being the most widely recognized due to its correlation with higher tumor grades and later clinical stages." (PMID 39851519, 2025). "Specifically, the attenuation of CD44 in MSCs was shown to significantly limit their expression of tumor-regulated CAF markers." (PMID 40244052, 2025). "The O2 microbubble propulsion system enables deep tumor penetration through mucus barriers under ultrasound guidance, with CD44-targeted chondroitin sulfate ligands facilitating selective tumor cell internalization." (PMID 40892295, 2025). "HA in the peritoneal glycocalyx can serve as a binding site for tumor cells through CD44, CD168 and ICAM-1." (PMID 41082053, 2025). "Anti-CTLA-4 and anti-PD-L1 therapies increase CD8+ T cell infiltration and CD44 expression, enhancing tumor cell contact and killing." (PMID 40995371, 2025). "As presented, there were the spatial enrichment of cell populations, including tumor cells exhibiting high CD44 expression, CAFs and TANs at the tumor’s edge." (PMID 40069574, 2025). "Specifically, the presence of CD44 in the ECM appears to be a pivotal factor in determining the responsiveness of tumor cells to CAR NK cells." (PMID 40075578, 2025). "β-catenin, a key component of the Wnt signaling pathway, was significantly upregulated in CD44+ cells, supporting its role in maintaining stemness and driving tumor progression." (PMID 39851519, 2025). "For instance, MZF1-mediated regulation of miR-328-3p acts as a tumor suppressor by modulating CD44 expression in the progression of STAD." (PMID 40655141, 2025). "The nanoparticle targets CD44‐expressing tumor cells via HA and, upon degradation by hyaluronidase in the extracellular matrix, undergoes size reduction and charged reversal to penetrate deep into the tumor." (PMID 40873650, 2025).
tumor (continued). "CD44 ectodomain shedding often occurs at the leading edge of migrating tumor cells, where it forms a complex with MMP14 to facilitate cytoskeletal interactions and tumor invasion." (PMID 41440277, 2025). "Others, including Ki-67, CD44, and p16, provide valuable insights for prognostic stratification and tumor staging." (PMID 40427131, 2025). "Hurt demonstrated that CD44+CD24- prostate stem-like cells isolated from the LNCaP cell line exhibited tumor-forming potential following the injection of as few as 100 cells into NOD/SCID mice." (PMID 40136652, 2025). "IMC identified more than 67,000 single cells in 11 distinct clusters, including antigen presenting cells, T cells, stroma cells, vascular cells and two clusters of proliferating and CD44/c-Myc positive tumor cells." (PMID 40395327, 2025). "Tumor cells potentially exploit MIF-(CD74+CD44) signaling to subvert immune surveillance, wherein MIF binding impairs immune effector functions." (PMID 40948800, 2025). "In the context of the crosstalk between tumor cells, stromal cells, and immune cells, the interplay between CD44 and SPP1 has been proposed to suppress CD8 + T-cell activation and foster tumor immune tolerance and evasion." (PMID 40524208, 2025). "In well-differentiated OOSCC, CD44 positivity was present in budding tumor cells at the invasive front." (PMID 40291275, 2025). "Transforming growth factor-β, epidermal growth factor, and fibroblast growth factor are factors that activate signaling pathways to upregulate CD44, promoting tumor cell survival, invasion, and resistance to chemotherapy." (PMID 40363706, 2025). "CD44 binds to hyaluronic acid, a major extracellular matrix component produced by both stromal and tumor cells." (PMID 40635786, 2025). "In the context of neoplastic diseases, CD44 acts in a multidirectional manner, promoting the malignant phenotype of cells." (PMID 41009438, 2025). "Downregulation of CD44 can lead to reduced tumor progression, impact cancer stem cell properties, alter critical cell signaling pathways." (PMID 40106490, 2025). "While tumor-rechallenge experiments are needed to fully confirm long-term immunity, the observed expansion of memory T-cell subsets (CD44+ CD62L−TEM) and sustained tumor-free survival strongly suggest that VVL-GL7 induces durable immune memory." (PMID 40299475, 2025). "The BC cell line MCF10DCIS.com, which forms ductal carcinoma in situ (DCIS) lesions in vivo, expresses high levels of CD44, have tumor initiating properties and are often used by researchers as a model for BC stem cells." (PMID 41374952, 2025). "The efficacy of CD44-targeted nanoparticles encapsulating PTX is shown by the efficient inhibition of tumor growth." (PMID 41367861, 2025). "Multiple CD44 isoforms are present in various cancer stem cells (CSCs) during tumor development and metastasis." (PMID 40244228, 2025). "It has been reported that the effector memory T cells (TEM, CD3+CD8+CD44+CD62L−) play an important role in killing tumor cells." (PMID 39780958, 2025). "CD44 is known to promote TNBC cell migration and invasion, and is associated with tumor metastasis and chemoresistance in TNBC patients." (PMID 40342488, 2025). "CD44 is a well-established marker for cancer stem cells or tumor-initiating cells (TICs) in the liver." (PMID 41509421, 2025). "In our study, flow cytometry analyses revealed that the cells isolated from the tumor tissue exhibited a CD44+/CD24− phenotype, CD61 positivity, high ALDH enzyme activity, and 49% CD133 positivity." (PMID 39932626, 2025). "Under pathological conditions, particularly in inflammatory and neoplastic diseases, activation of these pathways via CD44 can lead to uncontrolled cell growth or dysregulation of the immune response." (PMID 41009438, 2025). "By binding to CD44, sTN58 inhibits the invasive growth and hyaluronic acid-dependent tube formation in chemoresistant TNBC cells, where CD44 serves as a key driver of tumor cell aggressiveness and stem-like plasticity." (PMID 40342488, 2025).
tumor (continued). "In turn, high molecular weight (>100 kDa) tumor-derived hyaluronan (HA) in the tumor microenvironment binds to CD44 and activates the phosphatidylinositol 3-kinase (PI3K)/AKT/mammalian target of rapamycin complex 1 (mTORC2) signaling pathway." (PMID 40270603, 2025). "CD44 is widely recognized as a key marker for cancer stem cells in various solid malignancies, including GC, and has been extensively studied as both a tumor biomarker and a therapeutic target." (PMID 40849307, 2025). "Specifically, we identified CD44+ tumor cells, as well as CAFs and TANs infiltrated in TME, which exhibited a specific distribution in tumor edge region." (PMID 40069574, 2025). "The regulation of EMT by the TGF-β pathway enriches CSCs with high CD44 expression and increases the ability for tumor sphere formation in vitro." (PMID 39711287, 2025). "This subtype has been designated the mesenchymal cluster or normal-like/claudin-low and overexpresses genes associated with tumor invasive and aggressive features such as up-regulation of VIM, TGFB1 and SERPINE1/2 and cancer stemness such as CD44 expression." (PMID 38819630, 2025). "To investigate the tumor stemness in apple tumor cells, we used flow cytometric sorting technology to isolate tumor cells with high and low expression of CD44." (PMID 39866240, 2025). "Taken together, these data suggest that CD24+ tumor cells are more sensitive to HER2 inhibition-induced proliferation arrest, while CD44-expressing tumor cells display a survival advantage under therapeutic pressure." (PMID 40430044, 2025). "HA can promote tumour cell proliferation and survival through interactions with its receptors, primarily CD44 and RHAMM." (PMID 41465475, 2025). "Targeted administration of therapeutic drugs to cancer cells using CD44-specific nanocarriers has a role in suppressing tumor development and metastasis." (PMID 41367861, 2025). "For instance, CD44 facilitates vital cell–cell and cell–matrix interactions critical for tumor invasion." (PMID 40141751, 2025). "A ductal–permCAF pairing showed coordinated spatial variation between ductal PKM and permCAF CD44, consistent with metabolic remodeling in the tumor epithelium aligned with CAF-mediated adhesion and matrix engagement (Left)." (PMID 40964272, 2025). "Based on the expression levels of CD44, the tumor samples were divided into two groups: one group exhibited high CD44 expression, while the other exhibited low CD44 expression." (PMID 40069421, 2025). "Here, we found that Sin3a was markedly upregulated in CD44-high expressing cells by transcriptomic sequencing analysis of MMTV-MyPT tumor cells." (PMID 40409554, 2025). "CD44 appears to play a role in tumor metastasis and invasion by facilitating CSC attachment to the extracellular matrix, promoting tumor cell migration, and contributing to metastatic spread by binding to its ligand hyaluronic acid." (PMID 40422220, 2025). "Identifying biomarkers for treatment sensitivity is crucial, considering ferroptosis sensitivity across different tumor types and microenvironments as well as the context-dependent effects of CD44 on stemness." (PMID 40259468, 2025). "Target-modification strategies such as ligand conjugation with CD44 or EGFR can further improve tumor selectivity and therapeutic efficiency." (PMID 40943340, 2025). "HA-mediated motility is facilitated through the expression of the receptor for hyaluronan-mediated motility (RHAMM) and its interaction with CD44, which collectively promote tumor cell migration and invasion." (PMID 41156387, 2025). "In particular, the hyaluronic acid-CD44 axis in the tumor microenvironment promotes epithelial-to-mesenchymal transition, thereby further enhancing cancer cell invasion and migration." (PMID 41440277, 2025). "Inhibition with TG101209 and AZ960 reduces proliferation in tumorigenic SP/CD44+ cells, while momelotinib suppresses tumor growth by targeting JAK2 and downregulating PARP1 through the IFNGR-JAK2-STAT1-PARP1 axis." (PMID 41438763, 2025).
tumor (continued). "The results showed that CD44+ tumor cells can secrete pro-angiogenic factors, thereby promoting angiogenesis in HNSCC." (PMID 40703522, 2025). "Through engagement with CD44 and other receptors, HA regulates tumor cell motility, epithelial-to-mesenchymal transition, and resistance to apoptosis and chemotherapy, fostering malignant progression." (PMID 41155434, 2025). "Tumor-infiltrating CD8+ T cells from Ppp2cafl/fl/dLckcre mice exhibited reduced CD44+ cell population and markedly decreased IFN-γ production." (PMID 39759159, 2025). "For example, a study analyzed the expression of seven markers (ALDH1A1, ABCG2, various variants of CD44, CD133, CD271, and Nestin) in 40 cell cultures of primary strains and 40 tumor fragments, making a comparison with normal melanocytes and fibroblasts." (PMID 40806546, 2025). "Further, we found that the density of CD44+ and CD44+PTN+ tumor cells increased progressively from the tumor center towards the periphery, supporting our previous findings that CD44+ cells at the tumor leading edge secrete high levels of PTN." (PMID 40069574, 2025). "Adhesion molecules on peritoneal mesothelial cells can interact with receptors, such as CD44, on tumor cells, resulting in cytokine and Tumor Necrosis Factor alpha (TNFa) release, facilitating tumor cell attachment and invasion into the peritoneum." (PMID 41082053, 2025). "CD44 is known to have multiple functions, including promotion of tumor migration, invasion, proliferation, and recurrence." (PMID 40002787, 2025). "CD44 also serves as a marker for cancer stem cells (CSCs), which are responsible for tumor heterogeneity, recurrence, and therapy failure." (PMID 41439111, 2025). "The SPP1-CD44 axis was reported to be involved in tumor initiation and growth, and CD44 levels were found to be higher in AAH compared to AIS and IA." (PMID 40658605, 2025). "Western blotting showed that the levels of EMT‐related proteins were reduced in both PC cell lines after the addition of LMT‐28, and the expression of the tumor stem markers CD44 and CD133 was similarly reduced." (PMID 40874680, 2025). "This nanoparticle achieved cascade-enhanced drug delivery efficiency based on a relay strategy of deep tumor penetration, NO uptake by CD44 tumor cells, and HA release of a tumor microenvironment-sensitive drug." (PMID 39851489, 2025). "In the present study, tumor tissues obtained from GBM patients of Group E showed higher expression of CD44 and xCT in the tumor periphery than Group NE." (PMID 40002787, 2025). "Another pathway utilized by tumor cells to prevent apoptosis is signaling through the CD44/CD147/EGFR complex." (PMID 40114966, 2025). "HA, as a ligand for the tumor marker CD44, can also be decorated on the surface of NK cells to enhance tumor cell targeting by lipid insertion or click chemistry." (PMID 40114728, 2025). "The metastatic TIME of the lungs displayed high levels of Vimentin+, CD44+, tumor cells and F4/80+ TAMs." (PMID 40568104, 2025). "The interactions between CD44 and osteopontin in tumor progression, including invasion, metastasis, tumorigenesis, stemness, angiogenesis, and resistance to chemotherapy and radiotherapy, have also been reported." (PMID 40923026, 2025). "Inhibition of iRhom1 and thereby blocking subsequent ADAM17‐mediated shedding of CD44, enhanced tumor uptake of CD44 directed chemotherapeutics and increased tumor clearance in multiple cancers in mice." (PMID 41015904, 2025). "ER upregulates expression of the miR-29 family; opposing the effects of progesterone as an inhibition of miR-29a or miR-29b alone was sufficient to increase the tumor-initiating ability of CD44+ breast cancer cells." (PMID 40244378, 2025). "Mechanistically, CD44+ tumor cells at the edge can secrete PTN, a PDGF-inducible cytokine, which acts as a chemokine, aggregates CAFs, and leads to their transformation to iCAF-like or myCAF-like cells." (PMID 40069574, 2025).